MIR4766 (microRNA 4766)
Synonyms: hsa-mir-4766; mir-4766
Gene: MicroRNA gene on chromosome 22 (40,813,883 to 40,813,958, reverse strand). Ensembl gene ENSG00000266594.
Homologues: Orthologues: chimpanzee MIR4766 (100% identical).